TLR4 (toll like receptor 4)
Diseases named in the same sentence as TLR4 in open-access papers (continued):
Sharing a sentence is not in itself a finding about the gene and the disease.
bronchopulmonary dysplasia (2 papers, 2012 to 2013). Bronchopulmonary dysplasia is a chronic respiratory disease that results from complications related to lung injury during the treatment of infant acute respiratory distress syndrome in low-birth-weight premature infants or from abnormal lung development in older infants. "In a Canadian cohort which included mainly preterm infants, this TLR4 SNP occurred at a significantly lower frequency in infants without bronchopulmonary dysplasia (BPD) compared to those with diagnosed BPD." (PMID 23161283, 2013).
central nervous system infection (2 papers, 2017 to 2024). "TLR4, however, is also expressed by microglia, and TLR4 activation in microglia mediates inflammation in response to central nervous system infection." (PMID 28927423, 2017). "In bacterial and viral central nervous system infections, the participation of receptors TLR2 and TLR4 has been documented." (PMID 39553478, 2024).
cerebral artery occlusion (2 papers, 2021 to 2022). "Herein, we report a novel lipid-nanoparticle (LNP)-mediated knockdown of TLR4 in microglia and amelioration of neuroinflammation in a mouse model of transient middle cerebral artery occlusion (tMCAO)." (PMID 35745411, 2022). "In another study miR-155 was shown to regulate inflammation by promoting TNF- α and IL-1 ß expression via toll-like receptor 4 (TLR4) response in transient middle cerebral artery occlusion (tMCAO) model." (PMID 34756133, 2021).
chronic endometritis (2 papers, 2014 to 2020). A non-granulomatous or granulomatous chronic inflammation of the endometrium. "The results of the present study provide evidence of the critical role of TLR4 in human chronic endometritis." (PMID 25371751, 2014). "TLR4, a member of the TLR family, is highly expressed in the endometrial cells of the uterus and could thus be a key link between human chronic endometritis (CE) and the immune system." (PMID 25371751, 2014).
chronic gastritis (2 papers, 2015 to 2022). Inflammation of the stomach that is chronic in nature. "In this study we investigated for the first time the occurrence of alterations in the TLR2 and TLR4 mRNA and protein expression in H. pylori-infected patients with chronic gastritis, before and after successful bacteria eradication treatment." (PMID 25873761, 2015). "Thus, we evaluated the effect of eradication therapy on TLR2 and TLR4 mRNA and protein expression in H. pylori-infected chronic gastritis patients (CG-Hp+) and 3 months after treatment." (PMID 25873761, 2015). "A case-control study from Saudi Arabia showed that patients with TLR4-rs4986790 (A > G), TLR4-rs4986791 (C > T), and TLR10-rs10004195 (A > T) have a significant association with H. pylori infection, and TLR9-rs352140 (C > T) is connected with H. pylori-associated chronic gastritis." (PMID 35547123, 2022).
chronic lung disease (2 papers, 2025). According to the definitions of the American and British Thoracic Societies, including pulmonary functional tests, X-rays, and CT scans for items such as fibrosis, bronchiectasis, bullae, emphysema, nodular or lymphomatous abnormalities. "The enrichment of TLR4 rs10759932 CT genotype aligns with reports linking this variant to altered immune responses in chronic lung diseases." (PMID 41155286, 2025).
chronic pyelonephritis (2 papers, 2018 to 2019). "In our experiments, we observed beneficial effects of Zishenwan in chronic pyelonephritis rats and these beneficial effects might come from the secretion of SIgA in the urethral mucus and inhibition of TLR4 signal in rat bladder smooth muscle cell." (PMID 30519266, 2018).
cocaine addiction (2 papers, 2021). "On another hand, these findings offer innovative insights into the therapeutic effects of the widely available Ex4 on TLR4-associated neuroiflammation in an animal model of cocaine addiction." (PMID 34349653, 2021). "Indeed, previous evidence has shown that the GLP-1 receptor agonist Ex4, a known neuroprotective agent, suppresses TLR4 signaling, and modulates memory formation, which are heavily involved in cocaine addiction." (PMID 35024034, 2021). "On one hand, elucidating the mechanistic role of TLR4, IL-1β and TNF-α in cocaine-induced behavior is essential to ameliorate the understanding of progression and maintenance of cocaine addiction." (PMID 34349653, 2021).
colon disease (2 papers, 2010 to 2025). "Links to functional immune status and prognosis: In human colonic disease, TLR-4 and IL-6 expression in the tumor microenvironment were associated with adenocarcinoma." (PMID 41465346, 2025).
colon dysplasia (2 papers, 2014 to 2020). A morphologic finding indicating the presence of dysplastic glandular epithelial cells in the colonic mucosa. "We confirmed that TLR4 transcript levels were related to colonic dysplasia, CRC stage, and survival." (PMID 24887394, 2014). "We have leveraged available transcriptome databases and well-designed TMAs to address the biologic role of TLR4 in colon dysplasia." (PMID 24887394, 2014).
colon polyp (2 papers, 2019 to 2022). "Moreover, TLR4-deficient mice exhibit lower rates of colonic polyps." (PMID 31523496, 2019).
condyloma acuminatum (2 papers, 2014 to 2023). "The present study investigated the HMGB1, TLR4 and nuclear factor-κB p65 expression in condyloma acuminatum (CA) and verruca vulgaris (VV)." (PMID 25118798, 2014). "In addition, Brusatol can regulate the expression of Toll-like receptor 4 (TLR4) and inhibit the proliferation of genital warts keratinocytes, thereby regulating its progression." (PMID 38371913, 2023).
congenital toxoplasmosis (2 papers, 2013 to 2015). Toxoplasma infection that is present from birth. "The multiple SNP analysis indicated GTG variants at the TLR4 and TLR9 SNPs to be significantly less frequent in offspring with congenital toxoplasmosis than in uninfected offspring (p ≤ 0.0001)." (PMID 26254559, 2015). "The GTG multiple variants at the TLR4 and TLR9 SNPs were significantly less frequent among the fetuses and newborns with congenital toxoplasmosis than in the uninfected controls." (PMID 26254559, 2015). "Taking into account all the analyzed SNPs, the multiple ACG variant at the TLR4 896 A>G, 1196 C>T, and TLR9 1635 G>A polymorphic sites was most common among the fetuses and newborns with congenital toxoplasmosis, with a prevalence rate of 52.8 %." (PMID 26254559, 2015). "In this article, we present reasons for the research of the plausible role of SNPs residing in TLR2, TLR4, and TLR9 genes in congenital toxoplasmosis development." (PMID 23161283, 2013). "TLR4 and TLR9 SNPs seem to be involved in protection against congenital toxoplasmosis." (PMID 26254559, 2015). "We suppose that genetic modifications, especially of TLR2, TLR4, and TLR9, might play a plausible role in congenital toxoplasmosis development." (PMID 23161283, 2013).
Constipation (2 papers, 2015 to 2020). Infrequent or difficult evacuation of feces. "We therefore conclude that TLR4 may contribute to opioid-induced constipation." (PMID 25962524, 2015). "Hence, these results provide evidence that SHP alleviates PTX-induced constipation and intestinal morphological damage but augments the effects of PTX on the expression of cytokines in the TLR4 pathway and IL-1β." (PMID 32733972, 2020).
corneal disease (2 papers, 2022). "In contrast, in the mTLR4KO and their WT littermates, GLY significantly reduced corneal disease, TLR4, TLR9, HMGB1, and RAGE corneal mRNA expression after infection." (PMID 36422579, 2022). "Indeed, TLR4 plays a significant role in fungal killing because in TLR4 knockout mice, there is impaired fungal clearance and increased corneal disease." (PMID 36499260, 2022).
cutaneous squamous cell carcinoma (2 papers, 2021 to 2022). "TLR4 is expressed in human keratinocytes and its activation has been related to inflammatory, oxidative, and anti-proliferative effects, showing antineoplastic effects in cutaneous squamous cell carcinoma." (PMID 35163066, 2022).
cysticercosis (2 papers, 2013 to 2019). "Some studies have suggested that genetic abnormalities may be responsible for a high incidence of disseminated cysticercosis in the Indian population, and they noted that Toll-like receptor 4 gene abnormalities confer genetic susceptibility to disseminated cysticercosis as well." (PMID 31208369, 2019).
demyelination (2 papers, 2022 to 2023). "In conclusion, our findings for the first time indicate that Tregs alleviate myelin loss and improve cognitive function by inhibiting pyroptosis in microglia via TLR4/MyD88/NF-κB pathway in LPC-induced demyelination." (PMID 36803990, 2023). "PM enhances pathologic microglia activation in a TLR4/NF-kB-dependent manner leading to worsened demyelination disease in a murine model of EAE." (PMID 35199645, 2022).
Dengue hemorrhagic fever (2 papers, 2014 to 2018). A serious condition caused by Dengue virus infection. "Recent findings have uncovered that NS1 activates macrophages via Toll-like receptor 4 (TLR4) and disrupts endothelial cells which cause vascular leakage, a distinct characteristic of dengue hemorrhagic fever (DHF) and dengue shock syndrome (DSS)." (PMID 30914859, 2018).
dependence (2 papers, 2014 to 2021). "To determine whether TLR4 is required for the development of morphine physical dependence, we first assessed the behavioural signs of naloxone-precipitated withdrawal in morphine treated TLR4 mutant and null mice." (PMID 24824631, 2014). "Taken together, the behavioural and cellular indices of withdrawal suggest that TLR4 is not required for development of morphine physical dependence." (PMID 24824631, 2014).
Endoplasmic Reticulum Stress (2 papers, 2013 to 2015). Various physiological or molecular disturbances that impair ENDOPLASMIC RETICULUM function. "The purpose of this study was to investigate whether toll-like receptor 4 (TLR4) is implicated in the development of endoplasmic reticulum stress (ER stress) observed after a high-fat diet (HFD) in liver, skeletal muscle and adipose tissue." (PMID 23741455, 2013).
epithelial ovarian tumor (2 papers, 2018 to 2020). "Subsequently, we investigated the prognostic significance of PAUF and TLR4 expression in epithelial ovarian tumors." (PMID 30111860, 2018). "Interestingly, the expression of TLR-4 is observed in both the normal ovarian surface and epithelial ovarian tumor cell lines." (PMID 32455705, 2020).
Erythema (2 papers, 2021 to 2025). Redness of the skin, caused by hyperemia of the capillaries in the lower layers of the skin. "In turn, the percentage of all monocyte subpopulations expressing TLR4 correlated negatively with parameters assessed by a mexameter, especially on the cheek, i.e., erythema and melanin level." (PMID 41010653, 2025). "In WT mice, the skin became thick, and severe erythema, hemorrhage, edema, scarring and erosion were observed after Der p 38 administration; this skin severity was decreased in TLR4 KO mice." (PMID 34691014, 2021).
esophageal diseases (2 papers, 2021). "Could different TLR2 and TLR4 expression levels in oesophagitis be associated with disease-related changes in the oesophageal microbiome?" (PMID 33686512, 2021). "In oesophagitis, both nuclear and cytoplasmic TLR4 staining intensities were similar to those observed in normal epithelium, in both the basal and superficial layers." (PMID 33686512, 2021). "TLR4 plays a vital role in the pathogenesis of esophageal diseases." (PMID 34604113, 2021). "The factors explaining the unchanged TLR4 expression in oesophagitis are less obvious." (PMID 33686512, 2021). "Whether alterations in TLR2 and TLR4 expression levels have any specificity for the type of oesophagitis warrants additional studies." (PMID 33686512, 2021). "TLR2, TLR4 and FXR were expressed throughout normal squamous epithelium and in oesophagitis." (PMID 33686512, 2021). "Those authors found that in oesophagitis, TLR4 expression extended towards the epithelial surface, and that TLR4 mRNA levels increased in oesophagitis, but they provided no statistical data." (PMID 33686512, 2021). "Nuclear and cytoplasmic TLR4 was expressed throughout the thickness of squamous epithelium, with no change in oesophagitis." (PMID 33686512, 2021). "Therefore, our results confirmed the role of FXR in oesophagitis and support a link between FXR and TLR2 and possibly TLR4 responses." (PMID 33686512, 2021). "Here, we did not observe increased TLR4 expression in oesophagitis; however, we could not exclude TLR4 activation, since upregulation is not necessary to activate signalling." (PMID 33686512, 2021). "TLR4 recognizes mostly gram-negative species; however, TLR2 does also play a role in gram-negative infections, which probably in part explains the observed increase in TLR2 expression in oesophagitis." (PMID 33686512, 2021).
essential thrombocythemia (2 papers, 2021 to 2025). A chronic myeloproliferative neoplasm that involves primarily the megakaryocytic lineage. "Moreover, platelet TLR2 and TLR4 are important for the formation of platelet-neutrophil aggregates in patients with essential thrombocythemia." (PMID 34527000, 2021).
familial Mediterranean fever (2 papers, 2018 to 2021). Familial Mediterranean fever (FMF) is an autoinflammatory disorder characterized by recurrent short episodes of fever and serositis resulting in pain in the abdomen, chest, joints and muscles. "TLR4 SNPs that are responsible for asymptomatic bacteriuria might disturb the pathophysiology of familial Mediterranean fever without MEFV mutations." (PMID 30656032, 2018).
fibroids (2 papers, 2024 to 2025). "A study reported that the TLR4/MyD88/NFKB signaling pathway in primary cultured human fibroblasts from leiomyomas was activated under E. coli LPS treatment, which suggested that bacteria may be involved in the pathogenesis of leiomyomas by inducing cell proliferation through inflammation." (PMID 40041148, 2025). "There is only one report indicating activation of NF-kB and TLR4 in fibroid cells and uterine fibroid-derived fibroblast, and no published reports on MyD88 in fibroids." (PMID 38994944, 2024).
follicular lymphoma (2 papers, 2022 to 2023). Follicular lymphoma is a form of non-Hodgkin lymphoma characterized by a proliferation of B cells whose nodular structure of follicular architecture is preserved. "A recent phase 1/2 clinical trial assessed the therapeutic benefit to combine a TLR4 agonist (G100) with pembrolizumab in follicular lymphoma." (PMID 35990515, 2022).
gastric lymphoma (2 papers, 2013 to 2018). An extranodal lymphoma that arises from the stomach with the bulk of the mass located in the stomach. "A significant role in the genetic susceptibility of gastric lymphoma plays a rare allele of the Toll-like receptor 4 (TLR4 Asp299Gly)." (PMID 30364585, 2018).
Gastrointestinal dysmotility (2 papers, 2017 to 2025). Abnormal intestinal contractions, such as spasms and intestinal paralysis, related to the loss of the ability of the gut to coordinate muscular activity because of endogenous or exogenous causes. "Our findings provides the basis for a better understanding of the mechanisms underlying gastrointestinal dysmotility in presence of an anomalous neuroimmune cross talk, thereby paving the way for the development of suitable pharmacological modulators of TLR4 signaling for the management of GFD." (PMID 28642706, 2017).
gastrointestinal mucositis (2 papers, 2019 to 2022). "According to previous clinical studies, severe chemotherapy-induced gastrointestinal mucositis was prevented in TLR4 gene knockout mice." (PMID 35719331, 2022). "Moreover, the activation of TLR4 enhances IgA production, which is important for host resistance to chemotherapy-induced gastrointestinal mucositis." (PMID 31293986, 2019). "However, TLR4 knockout mice completely lack an IL-6 response, and IL-6 may be a more promising therapeutic target for preventing or alleviating chemotherapy-induced gastrointestinal mucositis." (PMID 35719331, 2022).
hypertrophic cardiomyopathy (2 papers, 2017 to 2020). A condition in which the myocardium is hypertrophied without an obvious cause. "Toll-like receptor 4 was observed to be perturbed in many cardiac diseases including diabetic and hypertrophic cardiomyopathy." (PMID 28690610, 2017). "Our previous studies illuminated that loss of MD1, a negative physiological regulator of the TLR4 signaling pathway, could worsen cardiac structural and electrical remodeling in a pathological condition, such as hypertrophic cardiomyopathy and ischemia/reperfusion injury." (PMID 32491968, 2020).
Hypoinsulinemia (2 papers, 2019 to 2025). A decreased concentration of insulin in the blood. "DT administration caused a similar degree of severe hypoinsulinemia in RIP-DTR; Tlr4−/− and RIP-DTR; Rage−/− mice and their littermate controls with intact TLR4 and RAGE, respectively, and S100A9 overexpression did not affect this parameter." (PMID 31391467, 2019).
inflammatory bone disease (2 papers, 2021 to 2023). "Toll-like receptor 4 (TLR4) is one of the best-characterized pattern recognition receptors in macrophages that respond to infection and microbial products, and is closely associated with bone homeostasis and inflammatory bone disease." (PMID 37596575, 2023). "Like many chronic inflammatory states in the bone microenvironment, TLR4 activation plays a crucial role in producing various pro-inflammatory cytokines such as TNF-α, IL-6, and IL-1β in macrophages, which stimulate OC formation and contribute to the pathology of inflammatory bone diseases." (PMID 37596575, 2023).
Jaundice (2 papers, 2017 to 2022). Yellow pigmentation of the skin due to bilirubin, which in turn is the result of increased bilirubin concentration in the bloodstream. "In addition, upon infection with Leptospira strain 56606v, TLR4−/− C57BL/6 mice presented more severe jaundice and liver injury as well as higher bacterial loads than WT mice but milder pulmonary hemorrhaging." (PMID 28536433, 2017).
kidney transplant (2 papers, 2015 to 2019). A surgical procedure in which one or both kidneys from a donor are implanted into a recipient. "Similarly, increased expression of the other member of toll-like receptors TLR4 was observed in kidney transplant recipients with chronic rejection compared to operationally tolerant patients." (PMID 26286066, 2015).
laryngeal squamous cell carcinoma (2 papers, 2016 to 2026). A squamous cell carcinoma that arises from the larynx. "Low nuclear expression of TLR4 has been previously linked to development of laryngeal squamous cell carcinoma." (PMID 27008696, 2016). "This study aimed to evaluate the association of TLR4 (rs7037225, rs11536889, rs7037117) and MYD88 (rs7744, rs6853) polymorphisms with the risk of laryngeal squamous cell carcinoma (LSCC), as well as its clinical and pathological characteristics and survival." (PMID 42278290, 2026).
lentivirus infection (2 papers, 2009 to 2013). Virus diseases caused by the Lentivirus genus. "TLR4 mRNA and protein expression were reduced in lung fibroblasts after TLR4-siRNA-lentivirus infection with an optimized inhibitory dose." (PMID 23305530, 2013).